NEU2 (neuraminidase 2)
Description:
Exo-alpha-sialidase that catalyzes the hydrolytic cleavage of the terminal sialic acid (N-acetylneuraminic acid, Neu5Ac) of a glycan moiety in the catabolism of glycolipids, glycoproteins and oligosaccharides. Recognizes sialyl linkage positions of the glycan moiety as well as the supramolecular organization of the sialoglycoconjugate. Displays preference for alpha- (2->3)-sialylated GD1a and GT1B gangliosides over alpha-(2->8)- sialylated GD1b, in both monomeric forms and micelles. Hydrolyzes monomeric GM1 ganglioside, but has no activity toward the miscellar form. Has lower sialidase activity for glycoproteins such as fetuin and TF/transferrin that carry a mixture of alpha-(2->3) and alpha-(2->6)-sialyl linkages. Cleaves milk oligosaccharide alpha- (2->3)-sialyllactose, but is inactive toward alpha-(2->6)-sialyllactose isomer. Has no activity toward colominic acid, a homomer of alpha- (2->8)-linked Neu5Ac residues.
Synonyms: SIAL2
Tractability: Small molecule: a structure with a bound ligand is known; a high-quality ligand is known. PROTAC: a small molecule that binds it is known.
Target class: Enzyme; Hydrolase
Gene: Protein-coding gene on chromosome 2 (233,023,032 to 233,042,480, forward strand). Ensembl gene ENSG00000115488.
Subcellular location: Cytoplasm, cytosol
Pathways (Reactome):
Metabolism: Glycosphingolipid catabolism
Metabolism of proteins: Sialic acid metabolism
Gene Ontology:
Molecular function: exo-alpha-sialidase activity; protein binding
Biological process: ganglioside catabolic process; glycoprotein catabolic process; oligosaccharide catabolic process; glycosphingolipid catabolic process
Cellular component: catalytic complex; cytosol; cytoplasm; lysosome; membrane
Genetic constraint (gnomAD): Loss-of-function variants: 11 observed, 8.44 expected, observed/expected ratio (o/e) 1.3, 90% interval 0.81 to 1.88. That is too few expected variants to judge how well the gene tolerates losing a copy. Missense variants: 509 observed, 523.58 expected, observed/expected ratio (o/e) 0.97, 90% interval 0.9 to 1.05. Synonymous variants: 208 observed, 231.03 expected, observed/expected ratio (o/e) 0.9, 90% interval 0.8 to 1.01.
Homologues: Orthologues: chimpanzee NEU2 (98% identical), macaque NEU2 (97% identical), pig NEU2 (77% identical), dog NEU2 (76% identical), rabbit NEU2 (71% identical), guinea pig NEU2 (70% identical), mouse Neu2 (69% identical), rat Neu2 (67% identical). Paralogues in human: NEU4 (44% identical), NEU3 (42% identical), NEU1 (26% identical).
Diseases named in the same sentence as NEU2 in open-access papers:
NEU2 is named in the same sentence as 43 diseases in open-access papers, as found by Europe PMC text mining. Sharing a sentence is not in itself a finding about the gene and the disease. The quoted sentences say what the papers report.
pancreatic cancer (5 papers, 2018 to 2022). "In a very recent observation from our group, we also established that association of cytosolic Neu2 with membrane triggers Fas-mediated apoptosis by impairing PI3K-Akt/mTOR pathway in pancreatic cancer cells (in press)." (PMID 29500369, 2018). "After comparing the status of Neu1/Neu2/Neu3/Neu4 in cancer and then in normal tissue specimens, it was concluded that the loss of Neu2 may aid in greater sialylation status in pancreatic cancer manifestation." (PMID 36547200, 2022). "Interestingly, α2,6-linked SAs are considered to be the main substrate for Neu2 in pancreatic cancer." (PMID 29434218, 2018). "It is interesting to note that in pancreatic cancer, α2,3linked SAs are thought to be the primary substrate for Neu2." (PMID 36547200, 2022). "This was corroborated with our earlier observation wherein we have reported that Neu2 overexpression activated an extrinsic pathway of apoptosis in pancreatic cancer cell lines." (PMID 32575925, 2020). "Patient tissues exhibited lower Neu2 as well as higher Shh than their normal counterpart, the same trends which have been followed in pancreatic cancer sphere-forming cells (PCS)." (PMID 32575925, 2020). "We checked the status of Neu2 in patient tissues by immunohistochemistry in randomly selected ten pancreatic cancer patient samples." (PMID 32575925, 2020). "As expected, we observed reduced sphere formation capacity, as well as higher sialylation status in the PCS, generated both from MIAPaCa2 and AsPC1 compared to adherent pancreatic cancer cell lines where Neu2 was overexpressed." (PMID 32575925, 2020). "The expression of cytosolic sialidase (Neu2) is much less both in pancreatic cancer cell lines and patient tissues." (PMID 32575925, 2020). "We have earlier reported lower mTORC1 and mTORC2 levels in Neu2-overexpressed pancreatic cancer cells." (PMID 32575925, 2020). "Overall, our study conclusively demonstrates the important role of sialidase Neu2 in reduced survival of pancreatic cancer sphere-forming cells which exhibited pancreatic cancer stem cell-like properties by modulating both Shh and mTORC2 axis." (PMID 32575925, 2020). "So far, we have shown that overexpression of Neu2 modulates the Hh pathway in pancreatic cancer sphere-forming cells." (PMID 32575925, 2020). "Recently, we have reported reduced expression of Neu2 in pancreatic cancer, the fourth leading source of cancer-related deaths worldwide." (PMID 32575925, 2020). "The important achievement of our study is the evidence that overexpressed Neu2 reduces the stemness-like properties of pancreatic cancer sphere-forming cells by desialylating an important molecule in the Hedgehog pathway." (PMID 32575925, 2020). "Taken together, Neu2 overexpression into pancreatic tumors generated in NOD/SCID mice led to reduction of tumor growth via modulation of mTOR/Hh axis thereby reducing stemness-like properties and inducing apoptosis." (PMID 32575925, 2020). "Due to lack of adequate understanding of the mechanism by which Neu2 regulates tumor cell behavior in pancreatic carcinoma, we aimed to explain the significance of Neu2 downregulation." (PMID 29434218, 2018). "However, the role of Neu2 in pancreatic cancer stem cells predominantly driven by the Hh-signaling pathway has received the least attention." (PMID 32575925, 2020). "We had previously reported that Neu2 reduces mTORC2 formation in pancreatic cancer cells." (PMID 32575925, 2020). "Therefore, crosstalk between Rictor, mTORC2 and Hh pathway in the context of Neu2 overexpression in pancreatic cancer sphere-forming cells have highlighted their effect in maintaining the stemness-like property." (PMID 32575925, 2020). "Taken together, our study ascertains a novel concept by which the function of Fas/CD95 could be modulated indicating a critical role of upstream Neu2 as a promising target for inducing apoptosis in pancreatic cancer." (PMID 29434218, 2018).
pancreatic cancer (continued). "Furthermore, we wanted to understand whether Neu2 has any role in the maintenance of stemness-like properties in pancreatic cancer sphere-forming cells." (PMID 32575925, 2020). "More importantly, this event shoved Neu2-overexpressed PCS toward apoptosis, suggesting Neu2 as a promising target for the initiation of cell death in pancreatic cancer sphere-forming cells." (PMID 32575925, 2020). "Therefore, it may be hypothesized that cytosolic sialidase Neu2, in general, preferentially aims at the extrinsic pathway-mediated apoptosis through targeting several membrane-bound molecules not only in different cancer cells but also in pancreatic cancer sphere-forming cells." (PMID 32575925, 2020). "Pancreatic cancer tissues showed reduced expression of Neu2 than adjacent normal tissues as reflected in optical densitometry score." (PMID 32575925, 2020).
breast carcinoma (3 papers, 2012 to 2023). "THY1 and NEU2 may be potential therapeutic targets for breast cancer with brain metastases, and THY1, CD1B and DOCK2 may serve as potential prognostic markers for improvement of brain metastases survival." (PMID 32867782, 2020). "Now we speculated that zanamivir may serve as an antineoplastic drug in breast cancer with brain metastases by targeting NEU2." (PMID 32867782, 2020). "Thus, we speculated that the upregulation of NEU2 may be involved in brain metastases of breast cancer through pathway of other glycan degradation." (PMID 32867782, 2020).
colon carcinoma (2 papers, 2014 to 2019). "Overexpression of sialidase Neu2 led to reduced metastasis, while Neu2 was found to be downregulated in highly metastatic variants of colon carcinoma." (PMID 24592356, 2014). "NEU4 was down-regulated in all EMT-induced cancer stem-like cells colon cancer cell lines DLD1, HT29 and LS174T, but not NEU1, NEU2 and NEU3." (PMID 30700826, 2019).
melanoma (2 papers, 2014). A malignant, usually aggressive tumor composed of atypical, neoplastic melanocytes. "In PC-3 prostate cancer and melanoma cells, Neu2 activity has been correlated with invasive and metastastatic potential; however, the biological substrates of Neu2 involved in this process remain to be identified." (PMID 25222608, 2014).
Obesity (2 papers, 2022 to 2025). Accumulation of substantial excess body fat. "A Neu2 knockout mouse model showed that loss of NEU2 abrogates lipid metabolism, resulting in hypertriglyceridemia, fatty liver, impaired muscle differentiation and motor function, ultimately leading to obesity-like phenotypes." (PMID 41301440, 2025). "Furthermore, we observed a noticeable increase of body weight in the Neu2 KO mice, suggesting an association between alteration of lipid metabolism and obesity." (PMID 35217678, 2022). "Because energy expenditure is related to obesity, we monitored body weight from 6 to 25 weeks of age in the Neu2 KO and WT littermate mice." (PMID 35217678, 2022). "As such, targeting neuraminidases, particularly NEU1, NEU2, and NEU3, may offer novel therapeutic strategies for obesity, type 2 diabetes, and NAFLD." (PMID 41301440, 2025).
prostate carcinoma (2 papers, 2014 to 2018). A carcinoma that arises from epithelial cells of the prostate gland. "NEU2 has the most dramatic results with regard to cancer; one study has shown that when NEU2 is overexpressed there is increased cell survival in prostate cancer." (PMID 29912148, 2018).
steatosis (2 papers, 2022 to 2023). Increased lipid within the cytoplasm of cells. "To explore this possibility, we assessed liver steatosis and observed severe steatosis in the livers of elderly Neu2 KO mice (> 41 weeks)." (PMID 35217678, 2022). "Notably, the lack of NEU2 abolished the lipid metabolism with severe, generalized consequences in homozygous knockout mice, such as serum hyperlipidemia, the lipid accumulation in the liver that causes severe steatosis in elderly animals." (PMID 37686385, 2023).
adenoma (1 paper, 2025). A neoplasm arising from the epithelium. "To investigate whether Neu2 contributes to TME remodeling during CRC progression, we used the CellChat package to compare intercellular communication networks across normal, adenoma, and cancer tissues." (PMID 40959269, 2025).
alcohol dependence (1 paper, 2019). Physical and psychological dependence on alcohol. "Neu2, for which response to ethanol is a biological process, has shown dysregulation in human embryonic stem cells exposed to alcohol and has been shown to be dysregulated in humans with alcohol dependence." (PMID 31140755, 2019).
Alzheimer disease (1 paper, 2022). A progressive, neurodegenerative disease characterized by loss of function and death of nerve cells in several areas of the brain leading to loss of cognitive function such as memory and language. "Sialylated glycoprotein analysis supported the involvement of Neu2 deficiency in brain-associated diseases such as amyotrophic lateral sclerosis, Alzheimer disease, and Huntington disease." (PMID 35217678, 2022).
colorectal tumor (1 paper, 2025). "Notably, Neu2 and Neu3 represented the predominant neutrophil subtypes in colorectal tumor (CT) samples, with Neu2 exhibiting an N2‐like phenotype and Neu3 exhibiting an N1‐like phenotype." (PMID 40842663, 2025).
coronary artery disease (1 paper, 2023). "Moreover, we prudently excluded three SNPs, namely rs1260326 in GCKR, rs34894639 in PPP2R3A, and rs2943652 in NEU2, owing to their known pleiotropic effects on a range of human traits, including T2DM, coronary artery disease, BMI, and triglycerides, as evidenced by PhenoScanner database searches." (PMID 37049421, 2023).
diabetes (1 paper, 2022). "We hypothesize that both abrogation of lipid metabolism and impairment of muscle function by Neu2 deficiency affect the knockout mice throughout life, consequently leading to fatty liver and diabetes." (PMID 35217678, 2022). "Surprisingly, knocking out the Neu2 gene in vivo abrogated overall lipid metabolism, impairing motor function and leading to diabetes." (PMID 35217678, 2022). "Our findings provide a rationale for use of the Neu2 KO mice as a model of early liver disease and diabetes." (PMID 35217678, 2022).
glioma (1 paper, 2021). A benign or malignant brain and spinal cord tumor that arises from glial cells (astrocytes, oligodendrocytes, ependymal cells). "Therefore, the effect of Neu2 on the amount of elastin in the skin was examined by using rat Neu2 expressed in C6 rat glioma cells." (PMID 33558588, 2021).
Headache (1 paper, 2023). Cephalgia, or pain sensed in various parts of the head, not confined to the area of distribution of any nerve. "Among the shared genes, four genes (NEU2, SLC44A4, and EHMT2 on chromosome 6, and STAC3 on chromosome 12) were associated with both migraine and headache." (PMID 36808568, 2023). "Among these shared genome-wide significant genes between migraine, headache, and glycemic traits, four (NEU2, SLC44A4, EHMT2, and STAC3) were common to both migraine and headache that overlapped more than one glycemic trait." (PMID 36808568, 2023).
ischemic stroke (1 paper, 2015). A stroke disorder caused by obstruction of blood flow to the brain, due to thrombotic (local blood clot formation) or embolic (due to a blood clot or other material traveling from another site) event. "Among the downregulated genes, Gpr88, Rgs9, Enthd1, Olr59, P2ry12, Degs2, Pde10a, Neu2, Adora2a, and Slc22a6 were found to demonstrate significant downregulation in pathological phase of ischemic stroke." (PMID 25861363, 2015).
metastatic tumors (1 paper, 2025). "Neu2 scores, calculated using five algorithms, were significantly elevated in primary and metastatic tumors compared to PBMCs." (PMID 40959269, 2025).
pancreatic ductal adenocarcinoma (1 paper, 2018). An infiltrating adenocarcinoma that arises from the epithelial cells of the pancreas. "There are few reports on sialyltransferase, however, the contribution of cytosolic sialidase (Neu2) remains unexplored in pancreatic ductal adenocarcinoma (PDAC)." (PMID 29434218, 2018).
pulmonary fibrosis (1 paper, 2017). Chronic progressive interstitial lung disorder characterized by the replacement of the lung tissue by connective tissue, leading to progressive dyspnea, respiratory failure, or right heart failure. "We also observed increased levels of NEU2 and NEU3 in mouse and pulmonary fibrosis, and observed that TGF-β1 can increase NEU2 and NEU3 in PBMC, and NEU3 in epithelial cells and fibroblasts." (PMID 29118338, 2017).
Sepsis (1 paper, 2022). Sepsis is defined as life-threatening organ dysfunction caused by a dysregulated host response to infection. "Four subtypes of neutrophils were identified in the peripheral blood of sepsis, namely, the Neu1, Neu2, Neu3, and Neu4." (PMID 36304125, 2022).
stomach cancer (1 paper, 2015). "We show that the amount of sialyl free N-glycans (FNGs) is dramatically reduced upon the co-expression of cytosolic sialidase NEU2 with cytosolic β-glycosidase GBA3 in human stomach cancer-derived MKN45 cells." (PMID 26193330, 2015). "The findings show that the amount of glycans is dramatically reduced upon the co-expression of cytosolic sialidase NEU2 with cytosolic β-glycosidase GBA3 in human stomach cancer-derived MKN45 cells." (PMID 26193330, 2015).
cancer (12 papers, 2015 to 2025). A tumor composed of atypical neoplastic, often pleomorphic cells that invade other tissues. "Neu2 overexpression causes desialylation of ɑ2,6- and ɑ2,3-linked SAs that are present on Atg5 protein in these cancer cells." (PMID 33526785, 2021). "Co-immunoprecipitation of Neu2 with Shh showed higher association of Neu2 with Shh in Neu2-overexpressed PCS (N-PCS) generated from both the cancer cell lines." (PMID 32575925, 2020). "α2,6-linked sialylation of Fas helps cancer cells to survive, which is a substrate for Neu2." (PMID 29434218, 2018). "Initially, we compared the status of Neu1/Neu2/Neu3/Neu4 in cancer and normal tissue specimens by immunohistochemistry." (PMID 29434218, 2018). "Given the pivotal role of ribosomes in cellular function as the factories for protein synthesis 33, we formulated the hypothesis that Neu2 may embody an abnormally functioning, cancer-specific subset of neutrophils." (PMID 40959269, 2025). "We found Neu2 overexpression enhanced different autophagy-related molecules in these cancer cells." (PMID 33526785, 2021). "Additionally, we demonstrated the role of overexpressed Neu2 both in apoptosis and anoikis through the induction of autophagy in these cancer cells." (PMID 33526785, 2021). "The expression of Neu2 is low in many cancers like colon adenocarcinoma and leukemia." (PMID 32575925, 2020). "To explore the role of Neu2 TANs in CRC progression, we mapped cancer cell trajectories using a pseudo-temporal spatial algorithm." (PMID 40959269, 2025). "Lee and colleagues propose that NEU2 and NEU3, expressed in cancer cells, play a role the impaired function of natural killer cells, thus helping cancer cells in terms of immune escape." (PMID 36009856, 2022). "We also observed that overexpressed Neu2 inhibited many molecules in the PI3K-Akt/mTOR pathway, which are aberrantly expressed during cancer progression." (PMID 33526785, 2021). "Four mammalian NEU homologues are known so far—NEU1, NEU2, NEU3 and NEU4—of which NEU 1, 2 and 4 are downregulated in various cancers, resulting in sialoglycan accumulation in cancer cells." (PMID 30478534, 2019). "Therefore, it may be envisaged that Neu2, in general, preferred to induce apoptosis through extrinsic pathway in cancer cells possibly independent of the type of cancer." (PMID 33526785, 2021).